CHTF18 (chromosome transmission fidelity factor 18)
Description:
Chromosome cohesion factor involved in sister chromatid cohesion and fidelity of chromosome transmission. Component of one of the cell nuclear antigen loader complexes, CTF18-replication factor C (CTF18-RFC), which consists of CTF18, CTF8, DCC1, RFC2, RFC3, RFC4 and RFC5. The CTF18-RFC complex binds to single-stranded and primed DNAs and has weak ATPase activity that is stimulated by the presence of primed DNA, replication protein A (RPA) and by proliferating cell nuclear antigen (PCNA). The CTF18-RFC complex catalyzes the ATP-dependent loading of PCNA onto primed and gapped DNA. Interacts with and stimulates DNA polymerase POLH. During DNA repair synthesis, involved in loading DNA polymerase POLE at the sites of local damage.
Synonyms: C16orf41; CTF18; CHL12; C321D2.4; C321D2.2; C321D2.3; RUVBL
Tractability: Small molecule: a structure with a bound ligand is known. PROTAC: ubiquitination databases record sites on it.
Gene: Protein-coding gene on chromosome 16 (788,046 to 800,737, forward strand). Ensembl gene ENSG00000127586.
Subcellular location: Nucleus
Subcellular location (Human Protein Atlas): Nucleoplasm; Cytosol
Pathways (Reactome):
Cell Cycle: Polymerase switching on the C-strand of the telomere
Gene Ontology:
Molecular function: DNA clamp loader activity; protein binding; single-stranded DNA helicase activity; DNA binding; ATP binding; ATP hydrolysis activity
Biological process: positive regulation of DNA-directed DNA polymerase activity; DNA replication
Cellular component: Ctf18 RFC-like complex; membrane; nucleoplasm; nucleus; chromosome
Genetic constraint (gnomAD): Loss-of-function variants: 151 observed, 100.94 expected, observed/expected ratio (o/e) 1.5, 90% interval 1.31 to 1.71. The synonymous counts are far from expectation, so gnomAD's model fits this gene poorly and the ratio says little. Missense variants: 1,982 observed, 1,266.6 expected, observed/expected ratio (o/e) 1.56, 90% interval 1.51 to 1.62. Synonymous variants: 916 observed, 549.44 expected, observed/expected ratio (o/e) 1.67, 90% interval 1.58 to 1.76.
Homologues: Orthologues: macaque CHTF18 (94% identical), chimpanzee CHTF18 (90% identical), pig CHTF18 (77% identical), mouse Chtf18 (75% identical), dog CHTF18 (75% identical), guinea pig CHTF18 (75% identical), rat Chtf18 (74% identical), tropical clawed frog chtf18 (55% identical), zebrafish chtf18 (47% identical), Drosophila melanogaster cutlet (32% identical), Caenorhabditis elegans ctf-18 (23% identical).
Diseases named in the same sentence as CHTF18 in open-access papers:
CHTF18 is named in the same sentence as 14 diseases in open-access papers, as found by Europe PMC text mining. Sharing a sentence is not in itself a finding about the gene and the disease. The quoted sentences say what the papers report.
endometrial carcinoma (2 papers, 2014 to 2023). A malignant tumor arising from the epithelium that lines the cavity of the uterine body. "Although CHTF18 and KMT5C have not been shown to correlate with RCC, they played a role in the development of other tumors; abnormalities in CHTF18 promoted endometrial carcinoma, and KMT5C played a role in non-small cell lung cancer." (PMID 36816355, 2023).
endometrial tumors (1 paper, 2014). "Our study uncovered nonsynonymous somatic mutations in ESCO1, CHTF18, and MRE11A in a subset of human endometrial tumors." (PMID 23755103, 2014). "We uncovered nonsynonymous somatic mutations in ESCO1, CHTF18, and MRE11A in, respectively, 3.7% (4 of 107), 1.9% (2 of 107), and 1.9% (2 of 107) of endometrial tumors." (PMID 23755103, 2014). "This is the first report of somatic mutations within ESCO1 and CHTF18 in endometrial tumors and of MRE11A mutations in microsatellite-stable endometrial tumors." (PMID 23755103, 2014).
Huntington disease (1 paper, 2021). Huntington disease (HD) is a rare neurodegenerative disorder of the central nervous system characterized by unwanted choreatic movements, behavioral and psychiatric disturbances and dementia. "The DNA polymerase Chtf18 (up-regulation assigned to Drd1-MSNs: pathogenic response that is aggravated then maintained) may be involved in DNA repair, a process genetically associated with human HD onset age (Genetic Modifiers of Huntington’s Disease (GeM-HD) Consortium, 2019)." (PMID 33618800, 2021).
Immunodeficiency (1 paper, 2025). Failure of the immune system to protect the body adequately from infection, due to the absence or insufficiency of some component process or substance. "Informatic analysis of WES data from the parents and proband revealed that the highest scoring variant was a component of a secondary clamp loader, CHTF18, a novel candidate in immunodeficiency." (PMID 40028343, 2025). "Indeed, together our data identify CHTF18 as a novel immunodeficiency gene that supports T cell development through its capacity to influence gene expression in a non-canonical manner, distinct from its traditional role as a secondary clamp loader." (PMID 40028343, 2025).
Infertility (1 paper, 2012). "The requirements for Chtf18 in mammalian spermatogenesis demonstrated above suggest that malfunctioning of CHTF18 may be a cause of oligospermia and infertility in men." (PMID 23133398, 2012).
lymphopenia (1 paper, 2025). Reduction in the number of lymphocytes. "Together, these data suggest that CHTF18 mutations like those in this patient are more likely to be associated with T lymphopenia than SCID; however, it remains possible that other variants that more severely attenuate CTF18 function, or alter canonical functions of CTF18, might cause SCID." (PMID 40028343, 2025). "Both the maternal (R751W) and paternal (E851Q) variants failed to complement the loss of zebrafish Ctf18 in restoring T cell development, supporting the conclusion that the patient’s compound heterozygous mutations in CHTF18 were responsible for the proband’s T lymphopenia." (PMID 40028343, 2025).
oligospermia (1 paper, 2012). Decreased number of spermatozoa in the semen. "To evaluate the impact of this severe oligospermia on fertility of Chtf18−/− males, we mated Chtf18−/− or wild-type males with pairs of wild-type females over a period of five months." (PMID 23133398, 2012).
tumor (5 papers, 2019 to 2023). "Differential gene expression analysis revealed 3155 DEGs (differentially expressed genes), among which six AAA ATPase genes (TRIP13, CHTF18, RFC4, ATAD2, FIGNL2, ATAD5) were significantly overexpressed in tumor samples compared to levels in normal samples." (PMID 31533816, 2019).
cancer (4 papers, 2020 to 2025). A tumor composed of atypical neoplastic, often pleomorphic cells that invade other tissues. "In line with such a functional relationship, POLE3, POLE4, DSCC1, CHTF18, and CHTF8 show a high correlation in co-essentiality score across cell lines as determined by the Cancer Dependency Map database." (PMID 36622344, 2023).
CHTF18 also shares sentences with these, for which no sentence is quoted: colon cancer (2 papers); autoimmune hepatitis (1); colorectal cancer (1); malaria (1); non-small cell lung carcinoma (1).